TRPM4 (transient receptor potential cation channel subfamily M member 4)
Diseases named in the same sentence as TRPM4 in open-access papers (continued):
Sharing a sentence is not in itself a finding about the gene and the disease.
cancer (continued). "In a zebrafish cancer model, TRPM4 knockout reduced metastatic burden and extravasation." (PMID 39821469, 2025). "Future inhibitors will have to prove that they block TRPM4‐related effects in 3D cancer systems." (PMID 39821469, 2025). "We performed a pan-cancer analysis of TRPM4 using TCGA data." (PMID 41584840, 2025). "In a parallel study, we discovered a unified mechanism of activity for both Acetalax and bisacodyl in cancer cells that likely involves the trapping of TRPM4 followed by its rapid degradation, cell membrane disruption, increased cellular volume, and mitochondrial defects with ATP depletion." (PMID 39932272, 2025). "TRPM4 was widely highly expressed in almost all the cancers." (PMID 36830651, 2023). "Moreover, our data suggest a more general role for TRPM4 in Ca2+-induced exocytosis in cancer cells with high levels of TRPM4 expression, such as PCa cells." (PMID 35681487, 2022). "CBA actions on cancer hallmark functions (cell viability, migration, cell cycle shift, and adhesion) seemed to be independent of TRPM4, as these processes were present in DU145 cells after the KO of TRPM4." (PMID 35056138, 2022). "To date, TRPM4 has been found to be upregulated in various cancers." (PMID 36147460, 2022). "The aberrant expression or malfunction of TRPM4 has been characterized in multiple diseases, such as cardiovascular, neurological, and skin diseases, as well as in different types of cancer." (PMID 35681487, 2022). "Manual inspection of the genes in this group revealed several genes that had not been associated with cancer stemness before, one of them being the TRPM4 gene, a member of the TRPM family of ion channels." (PMID 34680485, 2021). "We selected the transient receptor potential cation channel subfamily M member 4 (TRPM4) gene that had not been associated with cancer stemness before for further investigation." (PMID 34680485, 2021). "However, the role of TRPM4 in these cancers should be investigated at the cellular and molecular levels." (PMID 33562811, 2021). "Thus, CBA seems to be a promising inhibitor of human TRPM4, which is especially interesting for the cancer research field, where over-expression of human TRPM4 correlates with higher malignancy." (PMID 34335274, 2021). "The role of TRPM4 in cancer is often based on observations where it exhibits a different expression compared with control tissues; sometimes the correlation between the amount of TRPM4 expression and the prognosis and/or the post-treatment reoccurrence of the disease was studied." (PMID 35056097, 2021). "TRPM4 is expressed in many organs, including the heart, kidney, and brain, and is upregulated in specific cancer cells, rendering it a promising therapeutic target." (PMID 34335274, 2021). "TRPM4 expression levels have been investigated in a number of different cancers." (PMID 33562811, 2021). "Several studies have reported on the overexpression of TRPM4 in different types of cancer, and even though, its precise mechanism of action in tumors is currently unknown, it is already portrayed as a promising anticancer drug target." (PMID 34680485, 2021). "However, ROS-dependent alterations of TRPM4 activity in cancer cells have not yet been investigated and determining the contributions of TRPM4 to ROS-dependent alterations of Ca2+ signaling in cancer will be a challenge in the future." (PMID 33562811, 2021). "Nevertheless, the fact that TRPM4 is involved in the regulation of intracellular Ca2+ signaling in cancer cells is highly interesting, as Ca2+ oscillations and maintaining a cytosolic Ca2+ gradient in migratory cells were shown to contribute to cancer cell migration." (PMID 33562811, 2021).
cancer (continued). "Indeed, it was shown that Na+ influx via TRPM4 results in a decreased Ca2+ influx in many different cell types, including various immune and cancer cells." (PMID 34936030, 2021). "Lately, growing interest has been directed toward TRPM4 and its role in several types of cancer." (PMID 33562811, 2021). "In 2014, TRPM4 was described to be a cancer driver gene in androgen-independent PCa." (PMID 33562811, 2021). "Hence, TRPM4 is a potential prognostic cancer marker and a promising anticancer drug target candidate." (PMID 33562811, 2021). "Lately, the interest in studies on TRPM4 in cancer has increased." (PMID 33562811, 2021). "TRPM4 is known to be overexpressed in breast and other types of cancer." (PMID 34680485, 2021). "The precise mechanisms of action of TRPM4 in cancer are currently under investigation." (PMID 34680485, 2021). "We identified TRPM4 as an overexpressed ion channel that had not been associated with cancer stem cells before." (PMID 34680485, 2021). "The TRP family member TRPM4 has received much attention due to its implication in many physiological functions such as cardiac activity, immune response, cancer, arterial constriction, insulin secretion, and cell death." (PMID 34335274, 2021). "The pathways that mediate TRPM4 activity in cancer stemness are yet unknown; our preliminary data suggest that this ion-channel may be involved in the EMT process." (PMID 34680485, 2021). "Secondly, incubation with M4P downregulated TRPM4 expression on cell surface, most likely via a mechanism seen in therapeutic antibodies in cancer treatment, where the formation of receptor-antibody complex induces endocytosis and subsequent protein degradation." (PMID 31664513, 2019). "This could be due to post‐translational mechanisms that are altered in cancer cells and affect TRPM4 function, for example, glycosylation." (PMID 31441200, 2019). "In summary, TRPM4 contributes to cancer cell viability due to its ion conductivity." (PMID 31441200, 2019). "However, in cancer, these bioelectric cues, influenced by channels like TRPM4, may become dysregulated, leading to aberrant cell proliferation and migration." (PMID 40332161, 2025). "In contrast to previous studies using two‐dimensional (2D) cell systems, we here investigate the role of TRPM4 in PCa progression using three‐dimensional (3D) PCa tumor spheroids and a preclinical in vivo zebrafish model to access aspects of tumor formation and cancer development." (PMID 39821469, 2025). "Together, these results demonstrate that TRPM4 is a previously unknown target of Acetalax and bisacodyl and that TRPM4 expression in cancer cells is a predictor of Acetalax and bisacodyl efficacy and could be used for the clinical development of these drugs as anticancer agents." (PMID 39041239, 2024). "Therefore, TRPM4-dependent exocytosis might be involved in the regulation of cancer cell migration and/or contribute to polarized exocytosis in metastasis; however, further studies are needed to investigate that hypothesis." (PMID 35681487, 2022). "However, the mechanism of TRPM4 upregulation in cancer remains elusive." (PMID 36081847, 2022). "Interestingly, most studies on TRPM4 expression in cancer showed changes in the expression levels of TRPM4, but, so far, no TRPM4 mutations have been reported to be associated with cancer." (PMID 33562811, 2021). "However, TRPM4 still needs to be validated as a potential target in anti-cancer therapy." (PMID 34771564, 2021). "Analysis of genetic alterations in TRPM4 and SLC9A1 across cancers was performed using the cBioPortal platform, encompassing 32 studies and 10, 967 samples." (PMID 41235237, 2025). "We evaluated the distribution of the TRP family in C1–C6 pan-cancer immune subtypes and observed that TRPC4, TRPC6, TRPM4, TRPV2, TRPV4, MCOLN1, and PKD2L1 had the potential to predict the immune subtype." (PMID 36830651, 2023).
cancer (continued). "TRPM4 was highly expressed in CHOL, and TRPM6 exhibited significantly lower expression in pan-cancer tissues, particularly in COAD and READ." (PMID 36830651, 2023). "In these studies, the expression levels of TRPV4, TRPM2, TRPM4, and TRPM8 in cancer tissues are significantly increased, which is consistent with our OV research." (PMID 35813831, 2022). "In the following section, we provide an overview of how Piezo1/2, TRPC1, TRPC5, TRPM2, TRPM4, TRPM7, TRPV2 and TRPV4 affect cancer cell behavior." (PMID 36158191, 2022). "The expression profiling of several TRP ion channels, including the TRPC1, TRPM4 TRPML1 and TRPML2 genes, has been reported to predict the clinical outcome in cancer patients." (PMID 36499683, 2022). "In particular, we discuss the roles of Piezo1/2, TRPC1, TRPC5, TRPM2, TRPM4, TRPM7, TRPV2, and TRPV4 in mechanosensing and cancer metastasis." (PMID 36158191, 2022). "Meanwhile, restoring TRPM4 expression inhibits tumor cell growth both in vitro and in vivo, supporting it as a promising TSG in CRC and its methylation as a cancer-specific event." (PMID 36147460, 2022). "However, the actual role of TRPM4 in cancer development remains largely unknown." (PMID 34002002, 2021). "Contrarily, six ion channels are overexpressed in cancers and promote the activity of Wnt pathway (TRPC5, TRPV4, TRPM4, TRPM8, P2RX7, and ASIC1a)." (PMID 33117152, 2020). "Here, we investigated TRPM4 expression in a colon cell line (CCD 841 CoN) and cancer cell lines representing CRC in Dukes stage A (HCT116), B (LS180), C (HCT15), and D (Colo205)." (PMID 31441200, 2019). "Taken together, our data identify TRPM4 as a regulator of SOCE in hPEC and DU145 cells, demonstrate a role for TRPM4 in cancer cell migration and suggest that TRPM4 is a promising potential therapeutic target." (PMID 26496025, 2015). "TRPM4 is among the top significantly upregulated genes in PCa and the absence of TRPM4 reduced several cancer‐related functions in PCa cells in 2D PCa systems." (PMID 39821469, 2025). "The absence of TRPM4 in PCa cells reduced extravasation and metastatic burden in a preclinical 3D zebrafish cancer model." (PMID 39821469, 2025). "Interestingly, most investigations into TRPM4 and TRPM6 expression in cancer have reported alterations in their expression levels." (PMID 41562086, 2025). "Lastly, absence of TRPM4 in PCa cells reduced extravasation and metastatic burden in a preclinical zebrafish cancer model." (PMID 39821469, 2025). "Such bioelectric alterations underscore the need to understand TRPM4 and its interaction with the WNT/β-catenin and calcium signaling pathways, as these dynamics may offer insight into cancer progression and therapeutic targeting." (PMID 40332161, 2025). "In our study, the differential expression of TRPM2 and TRPM4 in tumor and para-carcinoma tissues was extremely clear, indicating the important role of these TRP family genes in the tumorigenicity in various cancers." (PMID 36830651, 2023). "Although our data did not allow us to demonstrate a direct mechanism to cancer formation, we showed associations of the CYBA and TRPM4 functions with ROS and mucin production with a likely link to tumorigenesis of CRC." (PMID 35158942, 2022). "Additionally, TRPC1, TRPC5, TRPM2, TRPM4, TRPM7, TRPV2 and TRPV4 can independently induce EMT in cancer cells." (PMID 36158191, 2022). "These small clusters of up to five cancer cells, called tumor buds, and an infiltrative tumor border configuration were correlated with lymphatic vessel invasion and lymph node metastasis in CRC, thereby linking TRPM4 expression to worse patient outcomes." (PMID 33562811, 2021). "TRPM4 may also be involved in the regulation of the Wnt/PCP signaling pathway, which is often aberrantly expressed in cancer." (PMID 34680485, 2021).
cancer (continued). "Transient receptor potential melastatin member 4 (TRPM4), a non-selective cation channel, mediates cell membrane depolarization in immune response, insulin secretion, neurological disorders, and cancer." (PMID 29568272, 2018). "Since we and others have found that compounds based on the ErSO chemical scaffold do not induce TRPM4 dependent cell swelling and lytic cell death in mouse cancer cells, we could not assess the effect of FGD3 on immunogenicity in syngeneic mouse models." (PMID 41225536, 2025). "In addition, lack of TRPM4 increased cell death in PCa tumor spheroids, a phenotype that is absent in two‐dimensional (2D) cancer cell systems." (PMID 39821469, 2025). "The nonselective cation channel TRPM4, activated by intracellular Ca2+ concentration ([Ca2+]i), has a relatively broad pattern of tissue expression and has been found to be upregulated in many human cancers 9,10." (PMID 36147460, 2022). "Although TRPM4 is nonpermeable to Ca2+, Na+ influx via TRPM4 decreases membrane potential and results in a decrease in intracellular Ca2+ signaling in many different cells, including rat dental pulp stem cells, various immune cells, and cancer cells." (PMID 33562811, 2021). "These atomic-level maps of TRPM4 facilitates ongoing development of specific TRPM4 inhibitors that can act through selectively obstructing its Ca2+-activation binding site or to inhibit TRPM4 via NBD binding, providing expanded avenues to therapeutically target TRPM4 in cancers." (PMID 32484822, 2020). "Transient receptor potential melastatin member 4 (TRPM4), a Ca2+-activated nonselective cation channel, has been found to mediate cell membrane depolarization in immune response, insulin secretion, cardiovascular diseases, and cancer." (PMID 29996905, 2018). "TRPM4 mRNA expression was analyzed in a nontransformed prostate epithelial RWPE‐1 cell line and two cancer‐derived cell lines, LNCaP and PC3." (PMID 28614631, 2018). "However, Na+ conductivity via TRPM4 contributes to the depolarization of the cell membrane, thereby reducing the driving force for Ca2+ entry through store-operated Ca2+ entry (SOCE), which is the main Ca2+ entry pathway in non-excitable cells, including cancer cells." (PMID 34771564, 2021).
tumor (37 papers, 2014 to 2026). "We calculated the risk scores (i.e., the number of tumours in which genes are risk factors minus the number of tumours in which genes are protective factors) and found that TRPM4 was the most significant risk factor." (PMID 35493463, 2022). "In the current study, our data illustrated a significant association between TRPM4 mRNA expression and tumor grade." (PMID 34936030, 2021). "TRPM4 protein was also shown to be highly expressed in tumor buds, which were linked to increased metastasis in CRC." (PMID 32182937, 2020). "CRC tissue characterized by higher TRPM4 staining intensity was associated with significantly more tumor buds in the TME." (PMID 31441200, 2019). "High TRPM4 protein expression in CRC is correlated with unfavorable tumor features (a high number of tumor buds, and a low TBC), associated with EMT, metastasis, and invasion." (PMID 31441200, 2019). "High TRPM4 protein expression was associated with unfavorable tumor features characteristic for epithelial–mesenchymal transition and infiltrative growth patterns, that is, a high number of tumor buds and a low percentage in tumor border configuration." (PMID 31441200, 2019). "The expression levels of ion-channel genes, including TRPM4, have been found to be predictive of and significantly associated with tumor progression." (PMID 28122498, 2017). "Future investigations using appropriate mouse models will be necessary to confirm the contribution of TRPM4 and its associated gene network to tumor growth control, as well as to elucidate their impact on the tumor immune microenvironment under physiological conditions." (PMID 41584840, 2025). "TRPM4 mutations may impair calcium ion permeability, leading to intracellular sodium/calcium imbalance and promoting tumor migration." (PMID 41235237, 2025). "In most studies, TRPM4 protein expression levels are reported to be elevated in tumor samples compared to healthy tissues." (PMID 41562086, 2025). "Tumor-related genes TRPM4, MYBL2, and CDKN2A were significantly upregulated and correlated with specific bacterial taxa." (PMID 40313460, 2025). "This was subsequently validated through immunohistochemical analysis, which confirmed the reduced TRPM4 expression levels in tumor tissues." (PMID 41584840, 2025). "Third, although a synergistic anti-tumor effect was observed between TRPM4 overexpression and NC1 treatment, the precise molecular mechanisms underlying this interaction remain incompletely defined." (PMID 41584840, 2025). "Here, we show that in a 3D PCa tumor spheroid model system, knockout of TRPM4 in PCa cells reduced tumor spheroid size, and outgrowth and increased cell death." (PMID 39821469, 2025). "From seven candidate NECSO regulators previously implicated in sodium homeostasis (NC1, CLT, DHPs, SLC12A2, SLC8A1, TRPM4, SLC9A1), intersection analysis identified two NECSO-associated DEGs - TRPM4 and SLC9A1 - showing consistent tumor-specific upregulation." (PMID 41235237, 2025). "Knockout of TRPM4 resulted in reduced PCa tumor spheroid size and decreased PCa tumor spheroid outgrowth." (PMID 39821469, 2025). "Functionally, restoring TRPM4 expression suppresses tumor cell proliferation, migration, and clonogenic capacity while inducing apoptosis, suggesting its potential role as a tumor suppressor in ccRCC." (PMID 41584840, 2025). "Flow cytometry using Annexin V-FITC/PI staining revealed a substantial increase in both early and late apoptotic cells upon TRPM4 overexpression, suggesting a pro-apoptotic, anti-tumor role for TRPM4." (PMID 41584840, 2025). "In contrast, higher TRPM4 expression was observed in tumor tissues of STAD, PRAD, LIHC, UCEC, PCPG, PAAD, CHOL and HNSC." (PMID 41584840, 2025). "This study systematically unveils the tumor-suppressive role of TRPM4 in ccRCC and innovatively establishes the NECSO Score as a robust prognostic model." (PMID 41584840, 2025).